CTSA (cathepsin A)
Diseases named in the same sentence as CTSA in open-access papers (continued):
Sharing a sentence is not in itself a finding about the gene and the disease.
cryptococcosis (2 papers, 2024). An acute or chronic, localized or disseminated infection by Cryptococcus neoformans. "Cpd1, a carboxypeptidase family member with homology to human cathepsin A, partially protects mice from experimental cryptococcosis when delivered in GP vaccines." (PMID 38712080, 2024).
glioma (2 papers, 2022 to 2024). A benign or malignant brain and spinal cord tumor that arises from glial cells (astrocytes, oligodendrocytes, ependymal cells). "Serum MGMT expression and CPTAC notably overlapped with respect to CTSA (upregulated in glioma and associated with immune infiltration), MTFHD1 (one-carbon metabolism association in GBM), and CD320 (implicated in a cobalmin-mediated metabolism)." (PMID 38612892, 2024). "To assess the value of CTSA in predicting the prognosis of glioma patients, we analyzed the association of CTSA expression with OS, DSS and PFI." (PMID 36381072, 2022). "It is suggested that CTSA may play a pro-carcinogenic role in the development of glioma and may be used as a biological marker to assess glioma risk classification, progress and targets for immunotherapy." (PMID 36381072, 2022). "We therefore hypothesized that CTSA may also serve as a potential diagnostic and prognostic biomarker in glioma." (PMID 36381072, 2022). "CTSA may serve as a candidate prognostic biomarker for determining prognosis associated with immune infiltration in glioma." (PMID 36381072, 2022). "The expression level of CTSA was compared between paired glioma tissues and normal tissues with Wilcoxon rank-sum test." (PMID 36381072, 2022). "In this study, bioinformatics analysis of the TIMER, UALCAN and TCGA public databases revealed higher levels of CTSA expression in glioma tissue than in normal glioma tissue." (PMID 36381072, 2022). "This study analyses the relationship between CTSA, and glioma based on The Cancer Genome Atlas (TCGA)." (PMID 36381072, 2022). "In this study, we try to prove the correlation between CTSA and glioma, then to analyze the prognostic role of CTSA in glioma based on RNA sequencing (RNA-seq) data from TCGA." (PMID 36381072, 2022). "Results showed that the prognosis of glioma patients was worse in the high CTSA expression group (HR=2.16 (1.69–2.76) P<0.001)." (PMID 36381072, 2022). "The clinical prognostic significance of CTSA in patients with glioma was then analyzed." (PMID 36381072, 2022). "Furthermore, we analyzed CTSA expression levels in glioma and normal tissue and determined the correlation between CTSA expression and patient prognosis in terms of overall survival (OS)." (PMID 36381072, 2022). "The CTSA was overexpressed in glioma tissues compared to normal tissues (P<0.001)." (PMID 36381072, 2022). "In summary, the present study demonstrated that CTSA was overexpressed in glioma and could predict prognosis by integrating and analyzing glioma-related information from the TCGA database." (PMID 36381072, 2022). "In addition, Kaplan-Meier survival analysis showed that patients with CTSA overexpression in gliomas had significantly lower survival rates than those with low expression." (PMID 36381072, 2022). "Taken together, our study suggests that CTSA is an important independent predictor of glioma." (PMID 36381072, 2022). "It was also hypothesized that CTSA could be a potential target for glioma immunotherapy." (PMID 36381072, 2022). "Cathepsin A (CTSA) is highly expressed in a variety of tumor tissues, but its role in glioma is poorly studied." (PMID 36381072, 2022). "Although many studies have found an effect of cathepsin on tumors, there is no reported correlation between CTSA and glioma." (PMID 36381072, 2022).
heart failure (2 papers, 2016 to 2020). Inability of the heart to pump blood at an adequate rate to meet tissue metabolic requirements. "Our proteomic and functional data suggest that cathepsin A inhibition has cardioprotective properties and support a beneficial effect of cathepsin A inhibition in the treatment of heart failure after myocardial infarction." (PMID 27246731, 2016). "Since initial phase 1 studies indicate a favorable safety profile for SAR1, our results encourage further investigation in cathepsin A inhibition for the treatment of post MI heart failure." (PMID 27246731, 2016). "Cathepsin A has recently gained attention as a promising target for the treatment of heart failure." (PMID 27246731, 2016).
myocardial infarction (2 papers, 2016 to 2025). Gross necrosis of the myocardium, as a result of interruption of the blood supply to the area, as in coronary thrombosis. "The cardiac expression of CTSA is upregulated in multiple animal models of myocardial infarction, Type 2 Diabetes and angiotensin II-stimulated hypertrophy." (PMID 40866338, 2025).
prostate carcinoma (2 papers, 2021 to 2023). A carcinoma that arises from epithelial cells of the prostate gland. "A previous study showed that knockdown of CTSA suppressed the metastasis of prostate cancer by reducing the phosphorylation of the P38 MAPK pathway." (PMID 34272452, 2021). "CTSA, a lysosomal protease, is upregulated in various cancers, including HCC and prostate cancer." (PMID 38053842, 2023).
acute kidney injury (1 paper, 2022). Sudden and sustained deterioration of the kidney function characterized by decreased glomerular filtration rate, increased serum creatinine or oliguria. "Further analyses that included vancomycin as an additional potential stressor revealed a common match for genes encoding cathepsin A, cathepsin C, cathepsin D and cathepsin S and an association of cathepsins with the lysosomal pathway, kidney disease and acute kidney injury." (PMID 35516525, 2022).
Alzheimer disease (1 paper, 2025). A progressive, neurodegenerative disease characterized by loss of function and death of nerve cells in several areas of the brain leading to loss of cognitive function such as memory and language. "They highlight the unique ability of APP among neurodegenerative disease-relevant substrates to be cleaved by CTSA and CTSH, and underscore the importance of systematically profiling these enzymes to better understand their potential roles in Alzheimer’s disease." (PMID 40671818, 2025).
aneurysm (1 paper, 2023). Bulging or ballooning in an area of an artery secondary to arterial wall weakening. "On the other hand, it was reported that the CTSA activity of a parietal thrombus of aneurysm was markedly increased compared to blood clot CTSA activity." (PMID 37202785, 2023).
aortic valve disease (1 paper, 2018). "In the current study, cathepsin A expression in the left atrium was significantly downregulated in MR patients in comparison with aortic valve disease patients and normal controls." (PMID 30581499, 2018). "Additionally, in comparison with aortic valve disease patients, MR patients had significantly downregulated CTSA and LNPEP expression and significantly upregulated MAS1 expression in the left atrium." (PMID 30581499, 2018). "Expressions of genes in the renin-angiotensin system, especially CTSA, LNPEP, and MAS1, in the left atrium in MR patients significantly differed from expressions of these genes in aortic valve disease patients and normal controls." (PMID 30581499, 2018). "Expressions of genes in the renin-angiotensin system, especially CTSA, LNPEP, and MAS1, in the left atrium in MR patients significantly differed from those in aortic valve disease patients and normal controls, and the differences were independent of circulating angiotensin II levels." (PMID 30581499, 2018).
cardiac hypertrophy (1 paper, 2016). "Cathepsin A (CTSA) is an interesting recent example, because not only is compound 8a [PMID 22861813] being explored to treat cardiac hypertrophy, but also an approved antiviral drug telaprevir is now being investigated for repurposing as a Cathepsin A inhibitor." (PMID 26464438, 2016).
cataract (1 paper, 2009). Partial or complete opacity of the crystalline lens of one or both eyes that decreases visual acuity and eventually results in blindness. "Cathepsins also seem to be involved in cataract-related processes since cathepsin A activity in the aqueous humor of cataract patients was found to be increased when compared to the aqueous humor of patients with other ocular diseases." (PMID 19597568, 2009).
chondrosarcoma (1 paper, 2025). A malignant cartilaginous matrix-producing mesenchymal neoplasm arising from the bone and soft tissue. "We analyzed a chondrosarcoma dataset, GSE30835, from the GEO database to evaluate the expression of nine cathepsins (cathepsin A, B, C, D, E, L, S, V, and Z) and found that three cathepsins, A, L, and V, showed notably higher expression in chondrosarcoma tissues than in normal cartilage." (PMID 39897041, 2025).
cystinosis (1 paper, 2019). Cystinosis is a metabolic disease characterized by an accumulation of cystine inside the lysosomes, causing damage in different organs and tissues, particularly in the kidneys and eyes. "Of note, although LAMP2A is cleaved by lysosomal cathepsin A and lysosomal protease inhibitors increase the amount of lysosomal membrane-localized LAMP2A in cystinosis, it is not yet clear whether this mechanism of LAMP2A upregulation may have direct implications in proximal tubule cell function." (PMID 30774622, 2019).
diabetes (1 paper, 2025). "The changes seen for DKK1, cathepsin A, cathepsin S, cathepsin Z, and FGF23 that potentially favor a bone resorptive state may contribute to the resorptive effects of RANKL in diabetes." (PMID 41373586, 2025).
diabetic cardiomyopathy (1 paper, 2025). Diabetic cardiomyopathy is a disorder of the heart muscle in people with diabetes. "CTSA and cathepsin B (CTSB) are capable of worsening diabetic cardiomyopathy and exacerbating cardiac impairment." (PMID 39964999, 2025).
hypoglycaemia (1 paper, 2025). "Following hypoglycemia, transient changes from baseline occurred in DKK1, cathepsin A, cathepsin G, cathepsin H, cathepsin S, cathepsin Z, parathyroid hormone (PTH), Sphingosine kinase 1 and 2 (SPK1/2), and interleukin-1 beta (IL1 beta) over the post-hypoglycaemia time course." (PMID 41373586, 2025).
leukodystrophy (1 paper, 2021). Leukodystrophies are a group of rare, progressive, metabolic, genetic diseases that affect the brain, spinal cord and often the peripheral nerves. "This underlines the limitation of panel sequencing, which unlike WES or WGS, does not allow for future re-analysis of DNA to detect for mutations in leukodystrophy genes that are discovered after initial panel curation (in this case the CLCN2, AARS, CTSA, and RNF216 genes)." (PMID 33597917, 2021).
liver fibrosis (1 paper, 2025). "Functional assays, including gene knockdown and overexpression experiments, are required to confirm the importance of key ECM genes (e.g. CTSA and ITGA1) in liver fibrosis and their potential as therapeutic targets." (PMID 40901642, 2025).
Mammary Adenocarcinoma (1 paper, 2020). "In this study, we investigated the concurrent effects of leptin on the lysosomal enzyme CTSA and the following effects on tumor cell proliferation and invasion capacity of CHMp, a canine mammary adenocarcinoma cell line." (PMID 33255835, 2020). "Therefore, in this study, we mainly focused on the alteration of metastasis of canine inflammatory mammary adenocarcinoma (CHMp) cells with leptin (with or without Allo-aca) and CTSA and further evaluated the alteration of CMA activity." (PMID 33255835, 2020).
myositis (1 paper, 2024). "In terms of myositis, marker genes encoding lysosomal proteins including cathepsins (CTSA, CTSK), IFI30 Lysosomal Thiol Reductase (IFI30) and CD74 Molecule (CD74) suggested active lysosome and immune cells activities in muscle turnover." (PMID 38342952, 2024).
neuroblastoma (1 paper, 2014). Neuroblastoma (NB) is the most common solid, extracranial childhood tumor. "The antibody used detected cathepsin A in human SH-SY5Y neuroblastoma cell lysates (data not shown)." (PMID 24101586, 2014).
oral cancer (1 paper, 2021). "Specifically, we assessed the expressions of cathepsin L (CTSL), cathepsin S (CTSS), cathepsin A (CTSA), and cathepsin Z (CTSZ) in platyphyllenone-treated oral cancer cells." (PMID 34065077, 2021).
tumor (18 papers, 2008 to 2025). "The Univariate Cox Regression analysis showed that tumor size (P = 0.033), TNM stage (P = 0.005), serum AFP level (P = 0.036), tumor differentiation (P = 0.008), vascular invasion (P = 0.048), and high expression of CTSA (P = 0.039) were risk factors affecting OS." (PMID 34272452, 2021). "The six-BMRGs risk score, comprising CD151, CTSA, MMP1, ROBO3, ADAMTS5 and MEP1A, was established for the prediction of clinical prognosis, tumor microenvironment characteristics, and immunotherapy response in HCC." (PMID 39070142, 2024). "TAM is mainly composed of M2 macrophages, and tumor immune infiltration analysis revealed that CTSA is closely related to immune-related pathways." (PMID 36381072, 2022). "For RFS, the vascular invasion (P < 0.001), tumor TNM staging (P < 0.001), Serum AFP level (P = 0.029), and high expression of CTSA mRNA (P = 0.003) were risk factors." (PMID 34272452, 2021). "The Multivariate analysis confirmed that tumor differentiation (HR (95%CI) 3.590 (1.093–11.795); P = 0.035) and high CTSA expression (HR (95%CI) 0.575 (0.336–0.983); P = 0.043) are independent risk factors affecting OS." (PMID 34272452, 2021). "We found that vascular invasion (P = 0.014), tumor TNM staging (P < 0.001), and high expression of CTSA mRNA (P = 0.006) were risk factors of overall survival by performing Univariate Cox Regression analysis." (PMID 34272452, 2021). "We found that the expression of CTSA mRNA in a variety of tumor tissues was significantly higher than normal tissues in the GEPIA database." (PMID 34272452, 2021). "Taken together, these results suggest that leptin and subsequent CTSA downregulation stimulate tumor invasion and metastasis via activation of the EMT process." (PMID 33255835, 2020). "It induces tumor cell dissemination and a significant increase in cathepsin A activity in lysates of metastatic lesions of malignant tumor was observed compared to primary focus lysates." (PMID 28106765, 2017). "In addition, Cathepsin A (CTSA), a lysosome-encapsulated cellular proteases, its abnormal expression promotes tumor growth and metastasis." (PMID 38114725, 2023). "In addition, the correlation between CTSA and immunosuppressive gene expression suggested that CTSA plays a key role in regulating tumor immunity." (PMID 36381072, 2022). "In addition, the mRNA expression of CTSA was incrementally upregulated with increasing neoplasm histology grades." (PMID 34272452, 2021). "The high protein level of CTSA was significantly correlated to the poor clinicopathological parameters, such as TNM stage, vascular invasion, tumor recurrence, and patient death of HCC." (PMID 38870261, 2024). "The overall tendencies were matched with mRNA expression, but leptin and knockdown of CTSA significantly upregulated MMP9 (matrix metalloproteinase 9), a biomarker of tumor invasion and metastasis." (PMID 33255835, 2020). "The high expression of CTSA mRNA was related to the vascular invasion (P = 0.001), tumor TNM stage (P = 0.004), serum alpha-fetoprotein (AFP) level (P = 0.001), neoplasm histology grades (P = 0.038), and adjacent hepatic inflammation in (P = 0.009) HCC patients." (PMID 34272452, 2021). "Interestingly, the knockdown of CTSA did not promote tumor cell proliferation but rather inhibited it." (PMID 33255835, 2020). "GB is a highly invasive tumor, interestingly we found that hypoxia did not induce MMP-2, MMP-9, PLAU, uPAR, CTSA, or ANXA2 gene transcription in our GB cell models." (PMID 32867190, 2020).
cancer (12 papers, 2017 to 2024). A tumor composed of atypical neoplastic, often pleomorphic cells that invade other tissues. "As reported, CTSA is overexpressed in various types of cancer and is linked to poor clinical outcomes." (PMID 38870261, 2024). "CTSA also has been identified as a potential biomarker for early diagnosis, prognosis and monitoring during cancer treatment." (PMID 34272452, 2021). "We analyzed the CCLE database and found that the CTSA mRNA expression copy number is significantly different in various kinds of cancer cell lines." (PMID 34272452, 2021). "In recent years, CTSA overexpression has been observed in various types of human cancers such as breast cancer, lung cancer, and prostate cancer." (PMID 34272452, 2021). "CTSA expression is higher in carcinoma tissues and may participate in extracellular matrix degradation." (PMID 38725063, 2024). "In summary, CTSA is significant in different cancers as a potential treatment target and predictor." (PMID 38053842, 2023). "The previous study has shown CTSA is abnormally expressed in various types of cancer." (PMID 34272452, 2021). "CTSA is a well-known serine protease cathepsin member of the cathepsin lysosomal protease family, which has been identified as a potential biomarker for early diagnosis, prognosis, and monitoring during cancer treatment." (PMID 34272452, 2021). "Due to the vital role played by lysosomes in cancer, a LRRS signature was constructed, including 8 genes, namely, CLN3, GBA, CTSA, BSG, APLN, SORT1, ANXA2, and LAPTM4B." (PMID 38114725, 2023). "Age, gender, family cancer history, preoperative radiotherapy, preoperative pharmaceutical, and body mass index (BMI) were not related to CTSA mRNA expression." (PMID 34272452, 2021).
infection (7 papers, 2005 to 2026). The state of being infected such as from the introduction of a foreign agent such as serum, vaccine, antigenic substance or organism. "When inspecting the quantitative data for other proteins in the renin-angiotensin system, two other proteins were found to be down-regulated 24 h post-infection, namely cathepsin A (CTSA) and angiotensinogen (AGT)." (PMID 32575076, 2020). "An enhanced level of cathepsin A was demonstrated during this infection." (PMID 31649671, 2019).
cardiovascular disease (2 papers, 2018). "To date, however, information regarding the role of cathepsin A (CTSA) in cardiovascular disease is still limited." (PMID 30581499, 2018). "CTSA inhibitors have been tested in humans, and CTSA is a therapeutic target for the treatment of cardiovascular diseases." (PMID 30018533, 2018).
metabolic disorder (2 papers, 2025). "Additionally, biallelic variants were detected in the CTSA and PEX1 genes, associated with severe metabolic disorders that often present with non-immune foetal hydrops." (PMID 41153384, 2025).
bacterial infection (1 paper, 2022). "It was reported that CTSA was significantly up-regulated in gill following V. anguillarum infection in turbot, which is consistent with our result that CTSAa and CTSAb were up-regulated the most in the gill compared with other tissues after bacterial infection." (PMID 36005507, 2022).
CTSA also shares sentences with these, for which no sentence is quoted: arteriopathy (5 papers); CADASIL (4); glycoprotein storage disease (3); hereditary diffuse leukoencephalopathy with spheroids (3); essential hypertension (2); Fabry disease (2); Hypertension (2); Sepsis (2); sialidosis type I (2); alopecia (1); asthma (1); autosomal dominant disease (1); autosomal recessive disease (1); breast ductal carcinoma in situ (1); cerebral small vessel disease (1); chronic hepatitis B virus infection (1); cognitive disorder (1); Coronary Artery Disease (1); developmental delay (1); genetic diseases (1); GM1 gangliosidosis (1); hepatitis C virus infection (1); HIV-1 infection (1); influenza (1); Intellectual disability (1); ischemic stroke (1); kidney disease (1); Lipid storage disease (1); Lysosomal disease (1); neuraminidase deficiency (1).
A further 10 diseases each share a sentence with CTSA in 1 paper.